DDX56 (DEAD-box helicase 56)
Description:
Nucleolar RNA helicase that plays a role in various biological processes including innate immunity, ribosome biogenesis or nucleolus organization. Plays an essential role in maintaining nucleolar integrity in planarian stem cells. Maintains embryonic stem cells proliferation by conventional regulation of ribosome assembly and interaction with OCT4 and POU5F1 complex (By similarity). Regulates antiviral innate immunity by inhibiting the virus-triggered signaling nuclear translocation of IRF3. Mechanistically, acts by disrupting the interaction between IRF3 and importin IPO5. May play a role in later stages of the processing of the pre-ribosomal particles leading to mature 60S ribosomal subunits. Has intrinsic ATPase activity. (Microbial infection) Helicase activity is important for packaging viral RNA into virions during West Nile virus infection. (Microbial infection) Plays a positive role in foot-and-mouth disease virus replication by inhibiting the phosphorylation of IRF3 leading to inhibition of type I interferon. (Microbial infection) Plays a positive role in EMCV replication by interrupting IRF3 phosphorylation and its nucleus translocation.
Synonyms: DDX21; NOH61; DDX26
Tractability: PROTAC: ubiquitination databases record sites on it; its protein half-life has been measured.
Gene: Protein-coding gene on chromosome 7 (44,565,418 to 44,575,051, reverse strand). Ensembl gene ENSG00000136271.
Subcellular location: Nucleus, nucleolus
Subcellular location (Human Protein Atlas): Nucleoli; Mitotic chromosome
Gene Ontology:
Molecular function: protein binding; protein sequestering activity; RNA binding; RNA stem-loop binding; RNA helicase activity; ATP binding; ATP hydrolysis activity; nucleic acid binding
Biological process: defense response to virus; host-mediated perturbation of viral RNA genome replication; negative regulation of type I interferon production; positive regulation of neuron projection development
Cellular component: cytosol; membrane; nucleolus; nucleus
Genetic constraint (gnomAD): Loss-of-function variants: 45 observed, 63.76 expected, observed/expected ratio (o/e) 0.71, 90% interval 0.56 to 0.9. The upper end of that interval is the gene's LOEUF score, 0.9, which puts it in group 3 of 6, group 1 being the genes least tolerant of losing a copy. Missense variants: 708 observed, 706.83 expected, observed/expected ratio (o/e) 1, 90% interval 0.94 to 1.07. Synonymous variants: 273 observed, 276.88 expected, observed/expected ratio (o/e) 0.99, 90% interval 0.89 to 1.09.
Homologues: Orthologues: chimpanzee DDX56 (99% identical), pig DDX56 (93% identical), rat Ddx56 (91% identical), macaque DDX56 (91% identical), mouse Ddx56 (91% identical), guinea pig DDX56 (91% identical), dog DDX56 (90% identical), rabbit DDX56 (87% identical), tropical clawed frog ddx56 (66% identical), zebrafish ddx56 (65% identical), Drosophila melanogaster Ddx56 (47% identical), Caenorhabditis elegans C24H12.4 (40% identical). Paralogues in human: DDX47 (27% identical), DDX27 (26% identical), DDX54 (25% identical), DDX18 (24% identical), DDX49 (24% identical), DDX31 (24% identical), DDX10 (24% identical), DDX24 (24% identical), DDX50 (23% identical), DDX1 (22% identical), DDX42 (22% identical), DDX51 (22% identical), and 26 more.